P3H3 (prolyl 3-hydroxylase 3)
Description:
Part of a complex composed of PLOD1, P3H3 and P3H4 that catalyzes hydroxylation of lysine residues in collagen alpha chains and is required for normal assembly and cross-linkling of collagen fibrils. Required for normal hydroxylation of lysine residues in type I collagen chains in skin, bone, tendon, aorta and cornea. Required for normal skin stability via its role in hydroxylation of lysine residues in collagen alpha chains and in collagen fibril assembly. Apparently not required for normal prolyl 3-hydroxylation on collagen chains, possibly because it functions redundantly with other prolyl 3-hydroxylases.
Synonyms: LEPREL2; GRCB; HSU47926
Tractability: Antibody: UniProt predicts a signal peptide or a membrane-spanning region; the Human Protein Atlas places it where antibodies can reach. PROTAC: ubiquitination databases record sites on it.
Gene: Protein-coding gene on chromosome 12 (6,828,381 to 6,839,854, forward strand). Ensembl gene ENSG00000110811.
Subcellular location: Endoplasmic reticulum
Subcellular location (Human Protein Atlas): Cytosol; Plasma membrane; Nucleoli
Pathways (Reactome):
Extracellular matrix organization: Collagen biosynthesis and modifying enzymes
Gene Ontology:
Molecular function: procollagen-proline 3-dioxygenase activity; iron ion binding; L-ascorbic acid binding; oxidoreductase activity, acting on paired donors, with incorporation or reduction of molecular oxygen
Biological process: negative regulation of cell population proliferation; collagen biosynthetic process; collagen metabolic process; peptidyl-lysine hydroxylation
Cellular component: catalytic complex; endoplasmic reticulum
Genetic constraint (gnomAD): Loss-of-function variants: 64 observed, 63.98 expected, observed/expected ratio (o/e) 1, 90% interval 0.82 to 1.23. The upper end of that interval is the gene's LOEUF score, 1.23, which puts it in group 5 of 6, group 1 being the genes least tolerant of losing a copy. Missense variants: 888 observed, 791.66 expected, observed/expected ratio (o/e) 1.12, 90% interval 1.06 to 1.19. Synonymous variants: 374 observed, 327.68 expected, observed/expected ratio (o/e) 1.14, 90% interval 1.05 to 1.24.
Homologues: Orthologues: chimpanzee P3H3 (99% identical), macaque P3H3 (97% identical), dog P3H3 (91% identical), pig P3H3 (90% identical), rabbit P3H3 (88% identical), rat P3h3 (87% identical), mouse P3h3 (87% identical), guinea pig P3H3 (84% identical), tropical clawed frog p3h3 (43% identical), zebrafish p3h3 (40% identical). Paralogues in human: P3H1 (42% identical), P3H2 (40% identical).
Diseases named in the same sentence as P3H3 in open-access papers:
P3H3 is named in the same sentence as 10 diseases in open-access papers, as found by Europe PMC text mining. Sharing a sentence is not in itself a finding about the gene and the disease. The quoted sentences say what the papers report.
breast carcinoma (1 paper, 2024). "Additionally, ENST000000536140 is a retained intron of P3H3 and is a new target for epigenetic silencing in breast cancer; however, its function in BLCA is unclear." (PMID 38482382, 2024).
glioblastoma (1 paper, 2009). The most malignant astrocytic tumor (WHO grade IV). "In ovarian, head and neck, vulval, melanoma, glioblastoma and renal carcinoma cell lines, P3H3 was clearly methylated and, as in breast cancer, this correlated with down-regulation of the mRNA (data not shown)." (PMID 19436308, 2009).
lung carcinoma (1 paper, 2024). "In contrast, based on our findings, we suggest that P3H3 functions as a novel form of cancer inhibitor, as its protein manifestation exhibits an inverse association with lymph node spread and tumor development in lung carcinoma." (PMID 38706607, 2024).
tumor (2 papers, 2023 to 2024). "We observed statistically significant associations for HIV total DNA and two tumor suppressor genes, NBL1 and P3H3, using a stringent false discovery rate q<0.05." (PMID 38019897, 2023). "The analysis of drug sensitivity indicated that increased expression of members from the P3H family, particularly P3H3 and P3H2, is strongly associated with heightened resistance to specific therapeutic drugs used for treating tumors, suggesting their role in mechanisms leading to tumor resistance." (PMID 38706607, 2024). "Notably, individuals with elevated expression of P3H2, P3H3, and CRTAP exhibited higher resistance to multiple anti-tumor drugs." (PMID 38706607, 2024).
P3H3 also shares sentences with these, for which no sentence is quoted: cancer (2 papers); colorectal cancer (1); gastric cancer (1); melanoma (1); renal carcinoma (1); tendinopathy (1).